TMPRSS2 (transmembrane serine protease 2)
Diseases named in the same sentence as TMPRSS2 in open-access papers (continued):
Sharing a sentence is not in itself a finding about the gene and the disease.
colorectal cancer (17 papers, 2020 to 2025). A primary or metastatic malignant neoplasm that affects the colon or rectum. "According to the results of single-cell RNA-seq analysis, TMPRSS2 was expressed not only in colorectal epithelial cells but also in master cells, macrophages, B cells and T cells in colorectal cancer tissues." (PMID 35017320, 2022). "A recent study using single-cell RNA-seq data demonstrated that TMPRSS2 is highly expressed in colorectal epithelial tissues and colorectal cancer." (PMID 35017320, 2022). "We further analyzed the expression of ACE2 and TMPRSS2 in single-cell RNA-sequencing profiling of 11 pairs of colorectal tumor and colorectal normal tissues from 11 patients with colorectal cancer patients in the GSE81861 dataset." (PMID 33479506, 2021). "In this study, we measured the expression of ACE2 and TMPRSS2 in colorectal cancer tissue samples from two publicly available databases by using bulk and single-cell RNA-sequencing (scRNA-seq)." (PMID 33479506, 2021). "Taken together, our findings demonstrate that TMPRSS2-TMPRSS4-TRIM31 genes are positively correlated together in colorectal cancer which may facilitate SARS-CoV-2 entry into cells." (PMID 35970857, 2022). "Notably, overexpression of ACE2 and TMPRSS2 have been observed in colorectal cancer including colon adenocarcinoma (COAD), and rectum adenocarcinoma (READ)." (PMID 34257580, 2021). "Furthermore, according to the pathway analysis of differently expressed genes (DEGs) with TMPRSS2 in lung, breast, ovarian and colorectal cancer, 160 DEGs genes were found and were significantly enriched in respiratory system infection and tumour progression pathways." (PMID 34951103, 2022). "Taken together, these observations indicate that TRIM31 gene expression is positively correlated with TMPRSS2 and TMPRSS4 in GI cell lines, solid tumors and colorectal cancer PDOs." (PMID 35970857, 2022). "A previous study identified colorectal cancer (CRC) as unique amongst human malignancies owing to its co-expression of higher levels of both ACE2 and TMPRSS2 than in normal tissues." (PMID 34834564, 2021). "Among the 203 epithelial cells of 266 cells in normal colorectal tissues, 21.7% of cells expressed ACE2 and 70.4% expressed TMPRSS2; among the 272 epithelial cells of 375 cells in colorectal cancer tissues, 13.6% expressed ACE2 and 48.2% expressed TMPRSS2." (PMID 33479506, 2021). "Importantly, higher co-expression of TMPRSS2 and TMPRSS4 relative to normal was also observed in a human gastrointestinal cancer cell line dataset and colorectal cancer organoids." (PMID 35970857, 2022). "We plan to include these additional colorectal cancer cell lines in future investigations to assess a broader range of drug responses and gene expression profiles, including ACE2 and TMPRSS2, enhancing the generalizability of the results and supporting the hypotheses presented." (PMID 41048966, 2025). "Also, in the GSE81861 dataset, among 103 non-epithelial cells from human colorectal cancer tissues, ACE2 was expressed by 33% of endothelial cells; TMPRSS2 was expressed by 7.6% of B cells, 5.9% of fibroblasts, 11% of macrophages, and 3% of T cells." (PMID 33479506, 2021).
Hypertension (17 papers, 2020 to 2025). The presence of chronic increased pressure in the systemic arterial system. "Treatment with H2S donors is known to alter virus receptors such as ACE2 and TMPRSS2 expression in atherosclerosis, hypertension, and cancer." (PMID 40388397, 2025). "Elevated expression levels of TMPRSS2 were also described in human pancreatic islets of obese donors compared with non-obese donors and in peripheral blood mononuclear cells (PBMC) of hypertension patients." (PMID 37208193, 2023). "Thus, while the TMPRSS2 and ACE2 proteins are some of the major targets of the coronaviruses, their excessive suppression by targeted therapies may result into the appearance of unprecedented collateral adverse effects such as the male infertility, frequent respiratory infections, and hypertension." (PMID 34647577, 2021).
Anosmia (16 papers, 2020 to 2024). An inability to perceive odors. "Herein, we evaluated the association of ACE1, ACE2, and TMPRSS2 expression with the presence of anosmia and/or ageusia." (PMID 36250059, 2022). "Although SARS-CoV-2 enters olfactory neuroepithelium via ACE2 receptor and TMPRSS2 and causes anosmia, we can speculate that chronic hyperglycemia might have caused damage to nerve fibers and olfactory network and contributed ultimately to reducing the occurrence of this symptom." (PMID 35957939, 2022). "Recent studies have shown that when SARS-CoV-2 enters the nasal and oral epithelium through the angiotensin-converting enzyme 2 (ACE2) and transmembrane serine protease 2 (TMPRSS2), it may cause damages to olfactory and gustatory receptor cells resulting in anosmia or ageusia." (PMID 34168250, 2021). "We explore ACE1, ACE2, and TMPRSS2 expression in these patients and the relationship of these genes with the onset of symptoms such as anosmia and ageusia." (PMID 36250059, 2022). "TMPRSS2 may also play a part in the ethnic variations in anosmia." (PMID 33996863, 2021). "People with PCC exhibit anosmia after SARS-CoV-2 infection because the virus enters the body through the olfactory epithelium and the expression of TMPRSS2 is upregulated in response to ACE2." (PMID 37940843, 2023). "TMPRSS2 is known to be essential in SARS-CoV-2 cell entry, suggesting a possible reason behind the higher burden of COVID-19 infection amongst African-Americans in the USA, possibly holding true for anosmia as well." (PMID 33996863, 2021). "Supporting this hypothesis is the rapid development of anosmia triggered by SARS-CoV-2, the high amounts of TMPRSS2 and ACE2 transcripts in sustentacular cells, and the critical role played by sustentacular cells in maintaining the integrity of the olfactory neuroepithelium." (PMID 32612515, 2020).
pneumonia (14 papers, 2021 to 2024). An acute, acute and chronic, or chronic inflammation focally or diffusely affecting the lung parenchyma, caused by an infection in one or both of the lungs (by bacteria, viruses, fungi, or mycoplasma.). "The initially lower incidence of pneumonia in BA.1 cases was thought to be due to a reduced ability to utilize the transmembrane protease serine 2 (TMPRSS2) pathway of cell entry, leading to a greater reliance on the cathepsin pathway." (PMID 39204013, 2024). "In this study, weinvestigated the expression of ACE2R and TMPRSS2 in the brainstem of 18 adult subjectswho died due to pneumonia/respiratory insufficiency." (PMID 37172190, 2023). "We used this approach and found unexpected decreases in key SARS-CoV2 molecules ACE2 and TMPRSS2 in two models of kidney lung cross-talk: 1) pneumonia and mechanical ventilation as a trigger of kidney injury and 2) AKI as a trigger of lung injury." (PMID 35123426, 2022). "After binding to angiotensin-converting enzyme-2 receptors (ACE2) and transmembrane protease serine 2 (TMPRSS2), SARS-CoV-2 enters the host cells and causes pneumonia with possible ARDS in the most severe cases." (PMID 34150807, 2021). "On the other hand, human targets, including many kinases, e.g., adaptor-associated kinase 1 (AAK1), cathepsin L, and the transmembrane serine protease 2 (TMPRSS2), are involved in the advancement of symptoms associated with SARS-CoV-2 infections, such as pneumonia, inflammation, and fibrosis." (PMID 36144718, 2022). "However, the common pneumonia cases caused by SARS‐CoV‐2 seemed to contradict the low co‐expression of ACE2 and TMPRSS2 in human lung cells, as revealed in this and previous reports." (PMID 35917402, 2022). "SARS-CoV-2 is an enveloped RNA virus and uses the spike protein (S) on viral envelope to attach to cellular receptors such as angiotensin-converting enzyme 2 (ACE2) and Transmembrane serine protease 2 (TMPRSS2) to enter human cells (especially lung cells), leading to severe pneumonia." (PMID 35632471, 2022).
prostatic intraepithelial neoplasia (13 papers, 2010 to 2025). "In parallel, King and colleagues demonstrated that transgenic TMPRSS2-ERG mice develop prostatic intraepithelial neoplasia (PIN) only in the context of PI3-kinase pathway activation when PTEN is inhibited or genetically ablated." (PMID 40427154, 2025). "IDC‐P exhibits a higher prevalence of TMPRSS2‐ERG fusions than prostatic intraepithelial neoplasia (PIN)." (PMID 38379333, 2024). "ETS aberrations are thought to be early events, and TMPRSS2‐ERG has previously been detected in high‐grade prostatic intraepithelial neoplasia (HGPIN)." (PMID 35574900, 2022). "Transgenic TMPRSS2-ERG mice develop prostate intraepithelial neoplasia, but only in the context of PI3K pathway activation." (PMID 31366128, 2019). "Homogeneous distribution of TMPRSS2-ERG fusion in 19% of high-grade prostatic intraepithelial neoplasia (PIN) lesions and in 50% of localized PCa suggests this fusion as either occurring after onset or associated with early events predisposing to clinical progression." (PMID 25520915, 2014). "The TMPRSS2:ERG fusion product can be found in 20% of prostatic intraepithelial neoplasia (PIN) adjacent to fusion positive cancer tissue but not in benign prostate tissue specimens or proliferative inflammatory atrophy (PIA)." (PMID 24281166, 2010). "The most frequent of these rearrangements create a TMPRSS2-ERG fusion gene, observed in ~15% of prostate intraepithelial neoplasia (PIN) and in ~50% of localized prostate cancer: this observation suggests that this genetic anomaly may represent an early event predisposing to tumor progression." (PMID 31366128, 2019).
pancreatitis (12 papers, 2020 to 2025). Inflammation of the pancreas. "Camostat mesylate, a TMPRSS2 inhibitor authorized for treating pancreatitis, has been confirmed to inhibit TMPRSS2 activity and prevent the fusion of the SARS-CoV-2 virus with the host cell membrane." (PMID 40724833, 2025). "Camostat mesilate, a protease inhibitor developed for the treatment of pancreatitis in Japan in the 1980s, was reported to inhibit TMPRSS2 and block the entry of SARS-CoV and SARS-CoV-2 into host cells." (PMID 35836239, 2022). "For example, the TMPRSS2 inhibitors camostat and nafamstat are protease inhibitors approved in Japan for treating pancreatitis, and known to inhibit TMPRSS2." (PMID 32839771, 2020). "The TMPRSS2 inhibitors camostat mesylate and nafamostat mesylate, medications used in pancreatitis, and bromhexine, a mucolytic, are currently under review in clinical trials." (PMID 32629804, 2020). "The drug has been clinically proven in oncological therapy and treatment of pancreatitis in Japan and shown efficacy in vitro in combination with cathepsin inhibitors in SARS-CoV infected human HeLa cells expressing ACE2 and TMPRSS2." (PMID 32719619, 2020).
chronic pancreatitis (11 papers, 2020 to 2024). A chronic inflammatory process causing damage and fibrosis of the pancreatic parenchyma. "Camostat, an inhibitor of transmembrane protease serine 2 (TMPRSS2), commercially available in Japan for treatment of chronic pancreatitis and postoperative reflux esophagitis, was found to inhibit viruses such as SARS-CoV 2 and Gram-positive bacteria." (PMID 33325009, 2021). "Notably, using an scRNA-seq data set of chronic pancreatitis, we observed the highest ACE2 and TMPRSS2 coexpression in male ductal (8.62%) and β cells (2.06%)." (PMID 34241597, 2021).
colon carcinoma (10 papers, 2016 to 2025). "For this, we employed human Caco-2 colon carcinoma-derived epithelial cells expressing TMPRSS2, a protease required for virus entry and that was reported to restrict responsiveness to SARS-CoV-2 infection toward treatment with CQN." (PMID 33918670, 2021). "Among the 140 epithelial cells in normal colon tissues, 5.7% of cells expressed ACE2 and 39.3% expressed TMPRSS2; among the 989 epithelial cells in colon cancer tissues, 12.3% expressed ACE2 and 38.5% expressed TMPRSS2." (PMID 33479506, 2021). "In human prostate and colon cancers, TMPRSS2 protein was found to be located on the apical membrane of secretory epithelia as well as in the lumen of the glands." (PMID 32764454, 2020). "TMPRSS2 is also expressed in colon cancer, hepatocellular carcinoma, human nasal and tracheal mucosa, distal airways, and lung." (PMID 32764454, 2020). "Caco-2 cells are a commonly used intestinal epithelial cell line derived from a colon carcinoma that also was shown to support robust replication of SARS-CoV-2, likely due to their high level of ACE2 and TMPRSS2 expression." (PMID 40196264, 2025). "Across the cohort, six fusion gene rearrangements were identified in cancers of the colon (TPM-NTRK1), bile duct (FGFR2), thyroid (BRAF) and prostate (ETV4-CLTC, and TMPRSS2-ERG)." (PMID 36213130, 2022). "In patients with colon cancer, ACE2 expression tended to increase with disease progression, whereas TMPRSS2 levels were not significantly altered in the lesions; however, patients with high levels of ACE2 displayed good prognosis compared to those with low expression." (PMID 33415119, 2020). "Also, in GSE146771, among 4231 non-epithelial cells from human colon cancer tissues, ACE2 was expressed by 3% of fibroblasts; TMPRSS2 was expressed by 12% of B cells, 21% of fibroblasts, 10.6% of innate lymphoid cells, 11.9% of macrophages, and 10.3% of T cells." (PMID 33479506, 2021).
endothelial dysfunction (10 papers, 2020 to 2025). In vascular diseases, endothelial dysfunction is a systemic pathological state of the endothelium (the inner lining of blood vessels) and can be broadly defined as an imbalance between vasodilating and vasoconstricting substances produced by (or acting on) the endothelium. "SARS-CoV-2 infection of ECs, via its receptor ACE2 and co-receptor TMPRSS2, can provoke endothelial dysfunction and disruption of vascular integrity, causing hyperinflammation and hypercoagulability." (PMID 34868042, 2021). "The P.1 variant of the SARS-CoV-2 is highly dependent on TMPRSS2 for its cell entry, and induces dramatic dysfunctional inflammatory and immunologic responses as well as a highly pro-thrombogenic endothelial dysfunction." (PMID 34976549, 2021). "Direct viral infection of ECs, via SARS-CoV-2 receptors, ACE2 and TMPRSS2, present on their surface, is able to provoke endothelial dysfunction and disruption of vascular integrity, leading to hyperinflammation and hypercoagulability." (PMID 34868042, 2021).
hepatocellular carcinoma (10 papers, 2021 to 2025). A malignant tumor that arises from hepatocytes. "We also studied entry pathways in human bronchial epithelial cells (Calu-3), human hepatoma cells (Huh7), and African green monkey kidney epithelial cells (Vero), which differentially express TMPRSS2." (PMID 40295839, 2024). "Through Western blotting analysis, a significant reduction in the expression levels of ACE2 and TMPRSS2 proteins was observed in HepG2 (human hepatocellular carcinoma) cells and HEK 293T (human embryonic kidney) cell lines without inducing cellular damage." (PMID 37894745, 2023). "A high protein expression of ACE2 and TMPRSS2 in HepG2 (hepatocellular carcinoma) and 293T (human embryonic kidney) cells was discovered in a screening model for SARS-CoV-2 entry into host cells." (PMID 36499094, 2022). "Hepatocellular carcinoma (HCC) HepG2 cells revealed high ACE2 levels and Huh7 expressed high TMPRSS2 protein are suitable models for mechanistic research of SARS-CoV-2 entry." (PMID 37964389, 2023). "Next, we orthogonally validated the observed protective phenotypes of inactivated NFKBIA, EIF4E2, and EIF4H by generating knockout lines from Huh7.5.1 (hepatocellular carcinoma) cells ectopically expressing ACE2 and TMPRSS2." (PMID 37803001, 2023). "Furthermore, investigations into the TMPRSS2 expression in hepatocytes from chronic hepatitis B (CHB) and hepatocellular carcinoma (HCC) patients revealed markedly elevated levels in HCC tissues compared to para-carcinoma tissues." (PMID 39858469, 2025).
Hyperglycemia (10 papers, 2017 to 2025). An increased concentration of glucose in the blood. "In our study, the effect of genistein on SGLT1, GLUT2 and TMPRSS2 expression raises the possibility that it could be a promising agent in reducing postprandial hyperglycaemia and SAR-CoV-2 infection risk." (PMID 40227199, 2025). "In this study, we examined the effect of some of the exposures associated with disturbed metabolism on TMPRSS2-ERG gene fusion, in particular, hyperglycemia and the potential role of IGFBP-2 in the latter." (PMID 29163372, 2017). "Here, our results show that hyperglycemia augments the expression of ACE2, TMPRSS2, and AXL receptors on BRB cells upon infection." (PMID 38598560, 2024). "One of the suggested mechanisms is hyperglycemia increasing expressions of angiotensin-converting enzyme 2 (ACE2) protein and transmembrane protease serine 2 (TMPRSS2), both of which are required for viral entry into human cells." (PMID 36219202, 2022). "Hyperglycaemia, instead of hyperinsulinaemia and hyperlipidaemia, can significantly induce the expression of SARS‐CoV‐2 entry factors (Ace2, Tmprss2, Tmprss4, Furin and Nrp1) in liver cells, but not in lung and pancreatic cells, which is attenuated by mTOR inhibition." (PMID 40442985, 2025).
chronic obstructive pulmonary disease (9 papers, 2020 to 2025). A chronic and progressive lung disorder characterized by the loss of elasticity of the bronchial tree and the air sacs, destruction of the air sacs wall, thickening of the bronchial wall, and mucous accumulation in the bronchial tree. "The lung airway expression of both ACE2 and TMPRSS2 is lower in children who are less susceptible to infection compared with adults, and significantly higher in smokers compared to non-smokers and in patients with chronic obstructive pulmonary disease (COPD) compared to healthy individuals." (PMID 36560732, 2022). "The elevated expression of ACE2, TMPRSS2, and FURIN in adults can be partially attributed to factors such as smoking and chronic obstructive pulmonary disease (COPD)." (PMID 40370452, 2025).
inflammatory bowel disease (9 papers, 2020 to 2025). A spectrum of small and large bowel inflammatory diseases of unknown etiology. "The GEO analysis indicate that PPARγ deficiency increased the expression of TMPRSS2 in induced inflammatory bowel disease." (PMID 34407143, 2021). "Further, along with ACE2, TMPRSS2 also increased in patients with inflammatory bowel disease responding to IL-12- and IL-23-targeted treatments." (PMID 40227199, 2025). "In this review, we explore the interplay among ACE2 and TMPRSS2 in the context of inflammatory bowel disease (IBD), including their roles in disease pathology and response to therapy." (PMID 41007801, 2025). "Nevertheless, ACE2 and TMPRSS2 expression sustained by inflammatory bowel disease is seemingly region-specific across the entire intestine, being found to be reduced in the inflamed ileum." (PMID 34399734, 2021). "ACE2 and TMPRSS2 are overexpressed in inflammatory bowel disease (IBD) patients." (PMID 37893427, 2023). "Pearson correlations between SGLT1, TMPRSS2, GLUT2 and ACE2 mRNA levels in human-derived ileum, colon and rectum tissue samples from patients with and without inflammatory bowel disease." (PMID 40227199, 2025).